ENSG00000291312 (novel protein)
Gene: Protein-coding gene on chromosome 19 (39,830,482 to 39,831,956, reverse strand). Ensembl gene ENSG00000291312.
Homologues: Orthologues: mouse Gm66680 (85% identical).